LINC00208 (long independently transcribed non-coding RNA 208)
Synonyms: C8orf14; NCRNA00208; VIR35
Gene: Long non-coding RNA gene on chromosome 8 (11,576,257 to 11,582,817, forward strand). Ensembl gene ENSG00000170983.
Diseases named in the same sentence as LINC00208 in open-access papers:
LINC00208 is named in the same sentence as 3 diseases in open-access papers, as found by Europe PMC text mining. Sharing a sentence is not in itself a finding about the gene and the disease. The quoted sentences say what the papers report.
endometriosis (1 paper, 2025). The growth of functional endometrial tissue in anatomic sites outside the uterine body. "The downregulation of LINC00208, a lncRNA with still poorly understood function, also suggests that non-coding elements may be modulating critical pathways in the uterus affected by endometriosis, disrupting its transcriptomic functionality." (PMID 40863222, 2025).
LINC00208 also shares sentences with these, for which no sentence is quoted: Barrett's oesophagus (1 paper); oesophageal adenocarcinoma (1).